CBX7 (chromobox 7)
Diseases named in the same sentence as CBX7 in open-access papers (continued):
Sharing a sentence is not in itself a finding about the gene and the disease.
pancreatic cancer (15 papers, 2011 to 2025). "Loss of CBX7 expression is associated with malignancy grade in human pancreatic cancer, whereas high expression of CBX7 in patients has a longer survival." (PMID 31709304, 2019). "Despite the fact that loss of CBX7 expression has been associated with enhanced malignancy in pancreatic cancer, the underlying molecular mechanism remains to be elucidated." (PMID 28030829, 2017). "In this study, we investigate the effect of CBX7 on pancreatic cancer development and explore the underlying molecular mechanisms." (PMID 28030829, 2017). "Previous studies have reported decreased CBX7 expression in thyroid, breast and pancreatic cancer, and the effects of its loss indicate CBX7 is a tumor suppressor." (PMID 28388562, 2017). "Likewise, loss of CBX7 is correlated with loss of E-cadherin and with a worse survival in pancreatic cancer patients." (PMID 31709304, 2019). "To explore the potential mechanisms underlying the tumor-suppressive role of CBX7 in pancreatic carcinogenesis, we further analyzed the signaling pathways that might be affected by CBX7 in pancreatic cancer cells." (PMID 28030829, 2017). "Our findings have established that DNMT1 represses the expression of CBX7 in pancreatic cancer, and that CBX7 contributes to the inhibition of pancreatic cancer progression." (PMID 40387566, 2025). "We investigated the expression of CBX7 in 6 pancreatic cancer cell lines and 1 human pancreatic ductal epithelial cell line HPDE by qRT‐PCR and western blot." (PMID 40387566, 2025). "For example, CBX7 is downregulated in pancreatic cancer and negatively regulates PTEN/Akt signal transduction during the development of pancreatic cancer." (PMID 34117289, 2021). "One study indicates that CBX7 suppresses cell proliferation through the suppression of the Akt signaling pathway in pancreatic cancer." (PMID 31709304, 2019). "Increased expression of CBX7 was inversely correlated with tumor grade and metastasis in pancreatic cancer." (PMID 28030829, 2017). "To further explore the involvement of CBX7 in pancreatic cancer development, we compared the expression of CBX7 and PTEN between PDAC and adjacent non-tumor tissues." (PMID 28030829, 2017). "In conclusion, we found that CBX7 plays a tumor-suppressive role in pancreatic cancer by the regulation of the PI3K/Akt signaling pathway." (PMID 28030829, 2017). "We used transwell chamber assay to explore the impact of CBX7 on the migratory capacity of pancreatic cancer cells." (PMID 28030829, 2017). "In the present study, we showed that CBX7 negatively regulates the proliferation, viability, chemoresistance, and migration of pancreatic cancer cells." (PMID 28030829, 2017). "To elucidate the potential role of CBX7 in pancreatic cancer development, we employed a lentivirus-based expression system to overexpress or deplete CBX7 in pancreatic cancer cells." (PMID 28030829, 2017). "Of note, CBX7 reduced PTEN/Akt signaling in pancreatic cancer cells by increasing PTEN transcription, suggesting involvement of PTEN/Akt pathway in the tumor suppressive activity of CBX7." (PMID 28030829, 2017). "Depletion of PTEN attenuated the influence of CBX7 on colony formation capacity in pancreatic cancer cells." (PMID 28030829, 2017). "In the present study, we provided in vitro and in vivo evidence to support a tumor-suppressive role of CBX7 in pancreatic cancer." (PMID 28030829, 2017). "CBX7 protein expression appeared to be inversely correlated with the malignancy grade of pancreatic cancer." (PMID 28030829, 2017). "In this regard, we found that CBX7 expression is decreased in pancreatic cancer cell lines and pancreatic tissues." (PMID 28030829, 2017). "We found that PTEN was upregulated in CBX7-overexpressing pancreatic cancer cells, compared with the control groups, whereas CBX7-depleted Panc-1 and MIA PaCa-2 cells exhibited reduced cellular PTEN." (PMID 28030829, 2017).
pancreatic cancer (continued). "Overexpression of CBX7 significantly inhibited the proliferation of pancreatic cancer cells in vitro and in vivo." (PMID 28030829, 2017). "Restoration of CBX7 expression impairs the tumor growth, migration, and invasion of pancreatic cancer in vivo and in vitro, whereas stable knockdown of CBX7 expression results in opposite phenotypes." (PMID 28030829, 2017). "Given the high mortality and limited therapeutic options for pancreatic cancer, understanding CBX7's role in its pathogenesis may reveal novel therapeutic targets." (PMID 40387566, 2025). "Studies have shown that CBX7 played an important role in gastric and pancreatic cancer." (PMID 33747044, 2021). "Because CBX7 is reportedly involved in pancreatic cancer malignancy, we analyzed whether the colony formation capacity was altered in these cells." (PMID 28030829, 2017). "In contrast, CBX7 was weakly expressed in most pancreatic cancer specimens." (PMID 28030829, 2017). "In addition, using linear regression analysis, we revealed that the expression of CBX7 was positively correlated with PTEN in patients with pancreatic cancer." (PMID 28030829, 2017). "CBX7 also impaired the viability and chemoresistance of pancreatic cancer cells." (PMID 28030829, 2017). "Next, we determined the prognostic merit of CBX7 expression in the patients with pancreatic cancer." (PMID 28030829, 2017). "CBX7, a member of the Polycomb-group proteins, plays a significant role in normal and cancerous tissues and has been defined as a tumor suppressor in thyroid, breast and pancreatic cancers." (PMID 28388562, 2017). "In addition, we identified that CBX7 inhibited the proliferation, migration, and invasion of cultured pancreatic cancer cells." (PMID 28030829, 2017). "Finally, our data showed that CBX7 overexpression suppressed pancreatic cancer progression in vivo." (PMID 28030829, 2017). "Our studies showed that CBX7 could regulate PTEN transcription in pancreatic cancer cells." (PMID 28030829, 2017). "Western blotting results revealed that the cellular level of CBX7 was markedly upregulated following CBX7-lentivirus infection in both Panc-1 and MIA PaCa-2 pancreatic cancer cells." (PMID 28030829, 2017).
hepatocellular carcinoma (13 papers, 2015 to 2024). A malignant tumor that arises from hepatocytes. "The Most of the studies have focused on single nucleotide polymorphisms of CBX4 and CBX7 and their association with reduced risk of hepatocellular carcinoma." (PMID 35677563, 2022). "Higher expression of CBX7 was correlated with better prognosis in hepatocellular carcinoma, whereas CBX1, CBX2, CBX3, CBX6 and CBX8 were identified as independent prognostic factors for poor overall survival." (PMID 35637952, 2022). "A previous study reported that the increased mRNA expression of HP1-β/γ (CBX1/3) and CBX2/6/8 was correlated with a worse OS, while the overexpression of CBX7 was related to a greater OS in patients with hepatocellular carcinoma." (PMID 34046352, 2021). "Moreover, mice knock-out for Cbx7 gene had a higher incidence of lung and liver carcinomas than heterozygous and wild type mice, suggesting the anti-oncogenic role played by the CBX7 protein in carcinogenesis." (PMID 25595895, 2015). "miR-181a promotes the development of hepatocellular carcinoma by regulating PTEN, CBX7, WIF1, and HOXB5." (PMID 36421826, 2022).
cervical carcinoma (12 papers, 2019 to 2025). A carcinoma arising from either the exocervical squamous epithelium or the endocervical glandular epithelium. "The aim of this study was to evaluate the association of the chromobox homologue 7 (CBX7) expression with the epithelial–mesenchymal transition in cervical cancer (CC), as well as with the disease prognosis." (PMID 33748425, 2021). "We found that CBX2, CBX4, and CBX8 presented notably increased expression, whereas PHC2, CBX6, and CBX7 presented decreased expression in cervical cancers." (PMID 39793896, 2025). "In line with this, downregulation of CBX7 promoted cell growth and migration as well as invasion in cervical cancer cells." (PMID 31709304, 2019). "Our RT-PCR results clearly showed that CBX7 mRNA level was significantly increased in cervical cancer cells after CBX7 cDNA transfection." (PMID 31709304, 2019). "In line with this, our study also showed that CBX7 overexpression inhibited cell growth and induced apoptosis in cervical cancer cells." (PMID 31709304, 2019). "Our RT-PCR results showed that CBX7 siRNA transfection decreased the mRNA level of CBX7 in cervical cancer cells." (PMID 31709304, 2019). "Next, we examined cell proliferation in cervical cancer cells after CBX7 downregulation by the MTT assay." (PMID 31709304, 2019). "The results from the wound-healing assay showed that CBX7 downregulation enhanced cell migration in both cervical cancer cell lines." (PMID 31709304, 2019). "We observed that overexpression of CBX7 inhibited cell growth and induced apoptosis in cervical cancer cells." (PMID 31709304, 2019). "We used molecular approaches to upregulate the expression of CBX7 or downregulation of CBX7 in cervical cancer cell lines." (PMID 31709304, 2019). "Consistently, the results from our western blotting revealed that CBX7 siRNA transfection downregulated the expression of the CBX7 protein in both cervical cancer cell lines." (PMID 31709304, 2019). "We found that overexpression of CBX7 inhibited cell proliferation in both cervical cancer cell lines." (PMID 31709304, 2019). "The mRNA level of CBX7 was measured by real-time RT-PCR analysis in cervical cancer cells after CBX7 cDNA transfection." (PMID 31709304, 2019). "CBX7 might also function as a tumor suppressor gene in cervical cancer, offering valuable insights for the diagnosis and potential targeted treatments of the disease." (PMID 37768206, 2023). "Decreased CBX7 expression is an independent predictor of the poor prognosis of cervical cancer." (PMID 35646140, 2022). "Chromobox homolog 7 (CBX7) is a member of the polycomb group family, which acts as a tumor suppressor in multiple human cancers, including ovarian carcinoma, pancreatic cancer, and cervical cancer." (PMID 35646140, 2022). "We found that CBX7 downregulation promoted cell proliferation in both cervical cancer cell lines." (PMID 31709304, 2019). "In the current study, we investigated whether CBX7 exerts its tumor-suppressive function in cervical cancer cells." (PMID 31709304, 2019). "Taken together, CBX7 could regulate the expression of E-cadherin and the nuclear factor-kappa B (NF-κB) pathway in cervical cancer cells." (PMID 31709304, 2019). "Moreover, a Transwell chamber invasion assay was performed to examine the invasive activity of cervical cancer cells after CBX7 overexpression for 20 h." (PMID 31709304, 2019). "The cell apoptotic death of both cervical cancer cell lines was induced by CBX7 overexpression." (PMID 31709304, 2019). "In the present study, we explore whether CBX7 exerts its tumor-suppressive function in cervical cancer." (PMID 31709304, 2019). "Therefore, we used a wound-healing assay to measure the migration in cervical cancer cells after CBX7 overexpression for 20 h." (PMID 31709304, 2019). "CBX7 overexpression retarded cell migration and invasion in cervical cancer cells." (PMID 31709304, 2019). "Herein, we report that CBX7 plays a tumor-suppressive role in cervical cancer." (PMID 31709304, 2019).
cervical carcinoma (continued). "We observed that CBX7 downregulation inhibited cell apoptosis in both cervical cancer cells." (PMID 31709304, 2019). "Moreover, cell growth and apoptosis were measured in cervical cancer cells after CBX7 overexpression or downregulation." (PMID 31709304, 2019). "Our findings suggest that CBX7 might be a tumor suppressor and could be a potential target in cervical cancer." (PMID 31709304, 2019). "Furthermore, cell migration and invasion were determined in cervical cancer cells after CBX7 modulation." (PMID 31709304, 2019). "Our results indicate that CBX7 regulates the cell apoptosis in cervical cancer." (PMID 31709304, 2019). "Our study will identify the role of CBX7 in cervical cancer." (PMID 31709304, 2019). "However, the functions of CBX2 and CBX7 are opposite in cervical cancer." (PMID 39793896, 2025). "Taken together, CBX7 could be a potential target in cervical cancer." (PMID 31709304, 2019). "It has been reported that CBX7 hinders HDAC2 activity to promote CDH1 expression and block epithelial-mesenchymal transition in thyroid, pancreatic and cervical cancer cells 19, 22-24." (PMID 35342353, 2022). "To determine further whether CBX7 overexpression was created in cells, we measured the downstream targets of CBX7, E-cadherin, and p65.10, 11 We found that overexpression of CBX7 increased the expression of E-cadherin but decreased the level of p65 in cervical cancer cells." (PMID 31709304, 2019). "Because CBX7 overexpression did not change the cell growth at 24 h (data not shown), CBX7 overexpression retarded cell motility in cervical cancer cells, not because of cell growth inhibition by CBX7 upregulation." (PMID 31709304, 2019). "The function of CBX7 in cervical cancer has not been elucidated." (PMID 31709304, 2019). "However, the biological functions and role of CBX7 in cervical cancer have not been elucidated." (PMID 31709304, 2019).
colon carcinoma (12 papers, 2014 to 2024). "For instance, loss of CBX7 expression represents an adverse prognostic marker for the survival of patients with colon cancer." (PMID 35646140, 2022). "CBX7 is associated with multiple clinicopathologic parameters in colon cancer." (PMID 34659360, 2021). "Moreover, CBX7 is downregulated in colon cancer and is associated with lymph metastasis and poor overall survival in patients with colon cancer." (PMID 31709304, 2019). "Therefore, we retain that the recent results evidencing a role of the loss of CBX7 expression in the progression of human colon cancer might be also explained by the ability of CBX7 to modulate the expression of several miRNAs." (PMID 28259135, 2017). "CBX7 presents a downregulated expression in multiple cancers, including pancreatic, cervical, breast, and colon cancers." (PMID 35646140, 2022). "The mRNA level of CBX7 in colon cancer samples is lower than that in normal colonic tissues, suggesting that the CBX7 expression is inhibited at the transcriptional level." (PMID 34659360, 2021). "miR-155 is positively regulated by CBX7 in MEFs and colon carcinomas, and has KRAS as one of the target genes likely accounting for the anti-apoptotic activity ascribed to miR-155 in some tissue contexts." (PMID 28259135, 2017). "Consistently, we report downregulation of both CBX7 and miR-155 expression in a set of colon carcinomas." (PMID 28259135, 2017). "A direct significant correlation (r = 0.6779) between CBX7 and miR-155 expression levels was found in a set of human colon carcinoma tissue samples." (PMID 28259135, 2017). "The direct correlation between CBX7 and miR-155 expression suggests that these genes are co-regulated in human colon carcinomas." (PMID 28259135, 2017). "The purpose of this study is to verify the tumor suppressor role of Cbx7 in human colon carcinomas (CC)." (PMID 25881303, 2015). "Results showed that transient Cbx7 overexpression significantly increased migration and invasion of colon cancer HCT116 cells." (PMID 25881303, 2015). "The contradiction between the two roles of CBX7 in colon cancer further suggests that multiple CBX7 regulatory pathways may exist." (PMID 34659360, 2021). "Indeed, mutations in the KRAS gene have been recurrently unveiled in numerous neoplasias comprising lung, pancreatic and colon carcinomas, where we have previously found a significant downregulation of CBX7 expression." (PMID 28259135, 2017). "Then, we have evaluated miR-155 and the CBX7 gene expression in colon carcinoma tissues by qRT-PCR." (PMID 28259135, 2017). "Human colon carcinoma samples have been investigated for the expression of CBX7 and miR-155." (PMID 28259135, 2017). "Whether downregulation of Cbx7 in stromal lymphoid cells involves in the progression of colon cancers should be studied further." (PMID 25881303, 2015). "CBX7 is suggested to help suppress the progression of human colon cancers." (PMID 25881303, 2015). "This suggests that the role of the exogenous Cbx7 overexpression in epithelial cancer cells might be different from that of the endogenous Cbx7 in colon cancer." (PMID 25881303, 2015). "Other studies have shown that the low CBX7 expression was an independent predictor for poor prognosis in colon cancers, and the CBX7 negatively regulates KRAS through miR-155 to inhibit the anti-apoptotic activity, suggesting that CBX7 may play a role as an antioncogene." (PMID 33748425, 2021). "However, the results of the Transwell tests and mouse experimental pulmonary metastasis assay showed that enforced Cbx7 overexpression might slightly increase the migration/invasion capacity of colon cancer cells." (PMID 25881303, 2015). "As shown in the interaction network, immune-related gene PLCG2 and IGF1, which are up-regulated in colon tumor samples, have significantly strong correlation with several TFs: FOXP3, IKZF1, CBX7, LMO2, MEF2C, EPAS1 and MAF." (PMID 33996273, 2021).
colon carcinoma (continued). "Compared with normal colonic mucosa, CBX7 expression is reduced or absent in a large number of colon cancer specimens, and the absence of CBX7 expression is remarkably correlated with the poor prognosis of colon cancer patients." (PMID 34659360, 2021). "As expected, the expression levels of P16INK4A and P14ARF were significantly higher in the P14AS expression-positive (+) samples than in the P14AS expression-negative (−) samples only within the CBX7 high colon cancer group, but not within the CBX7 low colon cancer group." (PMID 36176277, 2022). "The restoration of CBX7 expression in thyroid, gastric and colon carcinoma cell lines inhibits cell growth with an accumulation of the cell population in the G1 phase of the cell cycle, suggesting a negative role of CBX7 in the control of the G1/S transition of the cell cycle." (PMID 24865347, 2014).